CCND1 (cyclin D1)
Diseases named in the same sentence as CCND1 in open-access papers (continued):
Sharing a sentence is not in itself a finding about the gene and the disease.
cancer (continued). "In this paper, we report on identification of BRAFV600E, CCND1, and MYC mutations in a patient with synchronous triple primary malignant neoplasms, including malignant melanoma (MM), papillary thyroid carcinoma (PTC), and clear-cell renal cell carcinoma (ccRCC)." (PMID 37221610, 2023). "Additionally, the Western blot analysis revealed that the knockdown of SNHG3 significantly reduced the protein levels of proteins involved in the cell cycle (CDK6, CDK4, and Cyclin D1) as well as cancer metastasis (N-Cadherin, Vimentin, and MMP9)." (PMID 37348024, 2023). "Moreover, DSC1 was found to positively influence β-catenin, c-myc and cyclin D1 signaling pathways leading to cancer progression." (PMID 37620794, 2023). "Cyclin D1 (CCND1) is a critical regulator of the cell cycle and is known to facilitate uncontrolled cellular proliferation, making it a key player in the development of cancer." (PMID 37664052, 2023). "Importantly, overexpressing cyclin D1 restored the cell proliferation suppressed by MG53 in multiple cancer cell lines." (PMID 37414783, 2023). "CCND1 gene acts at the G1/S stage of the cell cycle and is frequently overexpressed in cancer." (PMID 36625087, 2023). "Cyclin D1 plays a pivotal role in physiologic hepatocyte proliferation, but is best known as an oncogene that is one of the most commonly overexpressed proteins in human cancers." (PMID 38152849, 2023). "CCND1 plays a significant role in the expression of various cancers." (PMID 38064496, 2023). "Also, the amplification or overexpression of cyclin genes, such as CCND1 and CCNE1, is associated with platinum resistance in various cancers." (PMID 37845393, 2023). "Cyclin D1 overexpression has been found in 32 to 88% of malignant tumors." (PMID 36982894, 2023). "According to the results of cell phenotype assays, the JAK1-STAT3 signaling downstream effectors, including VEGFA and CCND1, were screened out and their functions were uncovered in cancer cells, but themselves were also reported as METTL3-modified targets in a recent study." (PMID 38001065, 2023). "The role of cyclin D1 in cancer initiation and progression appears to be complex and multifaceted, and its contribution to carcinogenesis remains unknown." (PMID 36675501, 2023). "The binding of AZIN1 inhibits antizyme-1-mediated binding and degradation of the ornithine decarboxylase (ODC) and cyclin D1 (CCND1) oncoproteins, contributing to cancer initiation and progression, and controlling the proliferative and invasive abilities of cells." (PMID 37958449, 2023). "The increased JAK1 and STAT3 corporately contributed to the activation of the p-STAT3 signaling pathway and further upregulated downstream effectors expressions, including VEGFA and CCND1, which finally resulted in enhanced cancer cell proliferation and metastasis in vitro and in vivo." (PMID 38001065, 2023). "Similarly, the enforced expression of miR-34a (transfection of pre-miR-34a) was observed to target anti-apoptotic protein Bcl-2, c-Myc, Cyclin D1, E2F3 and Notch signaling pathway, causing the suppression of cancer cell proliferation, metastasis and invasion." (PMID 38139352, 2023). "Therefore, c-Myc and cyclin D1 have attracted considerable attention as potential targets for the treatment of cancer." (PMID 37064948, 2023). "MiR-211 has been found to bind directly to cyclin D1 mRNA and inhibit its expression in cancers." (PMID 37427143, 2023). "Although we cannot fully exclude other potential mechanisms, our results strongly suggest that the anti-cancer effect of MG53 is largely mediated by facilitating cyclin D1’s ubiquitination and subsequent degradation in multiple cancer cell types that depend on cyclin D1 for cell proliferation." (PMID 37414783, 2023). "Thus, our elucidation of CCND1 isoforms from different angles will contribute to better understanding the significance of CCND1 isoforms as a biomarker for cancer and targets for future therapeutic strategies." (PMID 37024471, 2023).
cancer (continued). "Some reports demonstrated that cyclin D1 overexpression may enhance the caspase-dependent and induced endoplasmic reticulum stress-mediated apoptosis in cancers." (PMID 36790653, 2023). "It is not uncommon that a protein has several E3 ligases, but the functions of the E3 ligases of cyclin D1 might be cancer-type and context dependent." (PMID 37414783, 2023). "miR-195 is involved in the regulation of cancer by targeting Cyclin D1, BCL-2, and YAP1." (PMID 38136338, 2023). "Moreover, we identified the miR-26a-1-3p site in the 3′ untranslated region (UTR) of GSK3β, MYC, and CCND1 mRNA, thus predicting a link between miR-26a and Met/GSK3β/MYC/CCND1 in cancers." (PMID 36672275, 2023). "In addition to CCND1, several other cancer-relevant genes, including MCL1, BCL2L1, CDC25, FAS, and HIF1A, were among the common genes." (PMID 36807142, 2023). "Upregulation of CTNNB1 and CCND1 may also increase cancer cell invasion, according to certain reports." (PMID 36708238, 2023). "Inhibition of SAAL1 expression could inhibit cancer cell proliferation, which may be related to the decreased expression of cyclin D1 and Bcl-2 proteins." (PMID 36973678, 2023). "Cyclin D1 is an important G1/S phase modulator for cell cycle control, its overexpression and dysregulation in cancer are the frequent events that may be sufficient for many malignant tumor development." (PMID 38031087, 2023). "The PI3K/Akt/mTOR pathway is known to stimulate cancer cell proliferation by mediating the transition from G1 to S phase during cell cycle progression through the activation of a cell-cycle regulator protein, cyclin D1." (PMID 37046823, 2023). "Current evidence suggests that mitogens, cytokines, and differentiation inducers could trigger Cyclin D1 (CCND1) protein expression in cancer cells." (PMID 36978140, 2023). "suppressed the proliferation of human cancer cell lines by decreasing cyclin D1 expression." (PMID 36840116, 2023). "In addition, cyclin D1 is abnormally up-regulated in many different types of human cancers as a proto-oncogene, including breast, lung, oesophagus, bladder, and lymphoid cancers." (PMID 37943017, 2023). "However, when it is abnormally activated, it can lead to the occurrence of cancer, including affecting the expression of downstream proteins such as cyclin D1 and c-myc and MMPs (matrix metalloproteinases)." (PMID 38202657, 2023). "Through computational simulation, we identified miR-26a bound to the 3′UTR of GSK3β/MYC/CCND1, thus suggesting a close association of Met/GSK3β/MYC/CCND1 and miR-26a promoting cancer proliferation, invasion, migration, drug resistance, and stemness metastasis in CRC patients." (PMID 36672275, 2023). "Thus, further studies leading to the development of optimization methods that enhance the anti-cancer effects of cyclin D1 inhibitors in PTC are warranted." (PMID 37427143, 2023). "Besides ODC, five other proteins that are upregulated in cancers have been identified as Az1 substrates to date, including DNp73 (encoded by TP73), Aurora A (AURKA), cyclin D1 (CCND1), Mps1 and Smad1." (PMID 37325974, 2023). "Similar to Bax and Bcl-2, c-Myc and cyclin D1 have been suggested as prognostic factors in cancer." (PMID 37064948, 2023). "Loss of FAT1 binding capacity for the key classical WNT pathway protein β-Catenin was caused by loss of FAT1 expression in cancer and therefore resulted in β-Catenin translocation to the nucleus and downstream expression effects such as regulation of target genes MYC and Cyclin D1." (PMID 36653435, 2023). "Research into the prognostic role of cyclin D1 in sinonasal (non-)ITACs could possibly give promising results for this carcinoma." (PMID 37370810, 2023). "For stage IV carcinomas, 31 out of 43 (72.1%) cases were strongly positive for cyclin D1." (PMID 37007344, 2023).
cancer (continued). "Furthermore, active STAT3 binds to human cyclin D1 promoters and raises cyclin D1, which is connected to cancer progression and development." (PMID 35566382, 2022). "Cyclin D1 has been reported to promote cancer progression in a variety of cancers." (PMID 35668070, 2022). "Amplification of FGF3/4/19 and CCND1 has been revealed in various cancers." (PMID 35814257, 2022). "Ki67 and cyclin D1 expression indicate the proliferative abilities of cancer cells." (PMID 35111269, 2022). "Cyclin D1, as a mitotic cyclin, plays an integral role in many types of cancer." (PMID 35059465, 2022). "CCND1 has a relationship with various cancers by regulating cell proliferation and differentiation." (PMID 35846330, 2022). "IHC revealed the upregulation of Myc, cyclin D1, and Wnt target genes in cancer cells." (PMID 35274815, 2022). "Therefore, elucidating the molecular mechanism that regulates cyclin D1 expression is of considerable significance for understanding the relationship between the cell cycle and the proliferation mechanism of malignant tumors." (PMID 33656636, 2022). "CCND1, as an important oncogene, has been reported in a variety of cancers." (PMID 35463335, 2022). "Cyclin D1 is a well-established oncogene that is overexpressed by many cancers." (PMID 35204045, 2022). "Moreover, in PLLs with progression, initial expression of Cyclin D1 were lower than in the cancer tissue during the follow-up (median: 5 (IQR 1–10) and 26 (IQR 10–40), p = 0.002)." (PMID 35626215, 2022). "However, the expression of cyclin D2 and cyclin D3 is rare compared with the universal expression of cyclin D1 in most cancers, and that cyclin D3 plays a unique role mainly in T-cell leukemia." (PMID 36059670, 2022). "Cyclin D1 is member of D cyclins that is usually upregulated in cancers including GBM." (PMID 35287551, 2022). "Hsa-miR-576-3p influencing PD-L1 and cyclin D1 could therefore directly interfere with cancer progression." (PMID 35409043, 2022). "In the early stage of cancer, failure to degrade cyclin D1 after double-strand DNA breaks (DSBs) may lead to the accumulation of DNA damage, thus promoting cancer development." (PMID 36059670, 2022). "In addition, vitamin K2 can reduce cyclin D1 expression in cancer cells by inhibiting the binding of the nuclear factor κB (NF-κB) to the cyclin D1 promoter, which occurs by arresting the cell cycle in the G1 phase." (PMID 36014904, 2022). "Thus, the evidence indicates that the frequent amplification and overexpression of cyclin D1 and B1 in cancer cells correlate with rapid cell proliferation." (PMID 35334562, 2022). "Finally, since FGF3/4/19/CCND1 genes are frequently amplified in many solid cancers, it is worthy to test this therapeutic strategy in other cancers beyond NSCLC." (PMID 35814257, 2022). "Therefore, cyclin D1 is regarded as one master regulator of cell proliferation, and its expression is usually dysregulated in human cancers." (PMID 35565262, 2022). "We further find the cell cycle drivers cyclin D1 (CCND1) and WEE1 to be repressed by AATK induction and identify the loss of AATK via epigenetic silencing as correlated to impaired overall patient survival in various cancers." (PMID 35902728, 2022). "Thus, although we observed that LY2874455 has an extraordinary effect on inhibiting FGFs/CCND1 amplification, it is essential to treat the cancer cells with CCND1 inhibitors to prevent acquired resistance through activation of CCDN1." (PMID 35814257, 2022). "Several studies showed that GPR30 activation could promote the proliferation of cancer cells via upregulating expression of cyclin D1, cyclin E, and cyclin A." (PMID 35096058, 2022). "Additionally, aberrant expression of FBXO4 has been previously documented in various cancers with accumulation of cyclin D1." (PMID 35272674, 2022). "Cyclin-D1 overexpression is correlated with malignant tumors." (PMID 35458590, 2022). "Several therapeutic agents have been shown to induce cyclin D1 degradation in cancer cells." (PMID 35548329, 2022).
cancer (continued). "Cyclin D1 is a metabolic checkpoint and a regulator of cell cycle machinery in cancer cells." (PMID 35411000, 2022). "Two of the individual CTCs (CTC1 and CTC2) and the CTC pool had homogenous copy-number profiles, and included amplification on 1q and 8q (MYC), 11q (CCND1, FGF3, FGF4) and allelic loss of regions including several cancer genes on 3p (BAP1), 13q(RB1, BRCA2) and 17p (MAP2K4)." (PMID 36088510, 2022). "Overexpression of cyclin D1 is generally detected in different types of malignant tumors 35, 36, whereas p21, as a cell cycle inhibitor and an antiproliferative effector in normal cells, is dysregulated in some cancers." (PMID 35664068, 2022). "Furthermore, failure to degrade cyclin D1 compromises the intra-S-phase checkpoint and results in high expression of cyclin D1, which is often witnessed in many kinds of malignant tumors, indicating poor prognosis." (PMID 36059670, 2022). "Next, given the key role of Cyclin D1 in cell proliferation and cancer, we asked whether pharmacological manipulation of pncCCND1_B expression could be exploited to modulate Cyclin D1 expression." (PMID 35326688, 2022). "In addition, it has been demonstrated that MCM7 promotes cancer progression through cyclin D1-dependent signaling." (PMID 35386284, 2022). "Our data show that chronic RT of PDAC cells results in upregulation of FDPS, cyclin D1, cyclin B1, and cancer stem cell markers in PDAC cells accompanied by altered cellular morphology, increased survival facilitated by G2/M arrest, and an increased side population." (PMID 34971971, 2022). "Moreover, treatment of cancer cells with dichloromethane and n-hexane extracts of Eryngium billardieri induced the overexpression of Bax and underexpression of cyclin D1." (PMID 35276978, 2022). "Nowadays, cyclin D1 has also been well characterized as a component of DNA repair machinery in human cancer cells; significant changes in the expression of this factor due to natural substances (e.g., parasitic products) other than commercial drugs, can promise an innovative therapeutic option." (PMID 36204226, 2022). "It has been reported that PGRN could activate these two pathways, resulting in increased expression of cyclin D1 and cyclin B and an enhanced proliferation rate in cancer cell." (PMID 35146924, 2022). "Constitutive activation can be found in several types of human cancer, and it is able to increase the level of different cancer-related molecules, such as surviving, Bcl-XL, cyclin D1/D2, C-Myc, Mcl-1, and vascular endothelial growth factor (VEGF), favoring tumorigenic progression." (PMID 35890348, 2022). "Cyclin D1, an important regulator of the cell cycle, participates in the transition from G0/G1 to the S phase and is commonly expressed at abnormally high levels in cancers." (PMID 36072972, 2022). "However, when free β-Catenin accumulates in the cytoplasm and enters the nucleus, it initiates the transcription of cyclin D1, a downstream target, leading to excessive cell proliferation and cancer." (PMID 35497881, 2022). "This indicates that the selective inhibition of CaN could be an effective method for the treatment of cancers that are characterized by cyclin D1 overexpression." (PMID 35163061, 2022). "Interestingly, DZIP3 has been shown to stabilize Cyclin D1 (CCND1) expression, which promotes cell-cycle progression and proliferation of cancer cells." (PMID 35993275, 2022). "Furthermore, KIS37 suppressed phosphorylation of Rb and cyclin D1 proteins, as well as the expression of cancer stem cell markers." (PMID 35276978, 2022).
cancer (continued). "However, cancer cells resistant to these CDK4 inhibitors still rely on CCND1 for proliferation, suggesting that new strategies to suppress CCND1-CDK4 are urgently needed." (PMID 35233069, 2022). "Moreover, c-MYC and CCND1 are markers of cancer cell proliferation and cell cycle progression, and western blotting showed that the expression of c-MYC and CCND1 was higher in the MED16 overexpression group." (PMID 36294896, 2022). "Additionally, trichothecin-induced apoptosis downregulates the expression of Survivin, XIAP, Bcl-xL, Bcl-2, and cyclin D1 via abrogation of NF-κB activation in human cancer cells featuring constitutively active NF-κB." (PMID 35955813, 2022). "Therefore, high levels of CKIε promote major PER degradation, and consequently increase the levels of cyclin D1 and cyclin E in cancer cells, promoting its proliferation." (PMID 35897788, 2022). "Given their FDA-approval, the pleiotropic effect of PPIs to maintain the expression of Bax and to decrease cyclin D1 levels may be an attractive strategy to overcome the resistance of cancer cells to radiation therapy." (PMID 35992826, 2022). "Cyclin D1 promotes cancer development by regulating cell cycle progression." (PMID 35287551, 2022). "This study showed that the expression of cyclin D1 was significantly increased after PLAC8 overexpression, suggesting that PLAC8 may also promote cancer by regulating cyclin D1." (PMID 35497881, 2022). "Copy number amplifications are frequently observed in the chromosomal region 11q13, which harbors besides ANO1, genes CCND1, ORAOV1, PPFIA1, FADD and CTTN, the expression of which is associated with cancer proliferation, migration, apoptosis or poorer prognosis." (PMID 33803266, 2021). "Cyclin D1, as a cell proliferation promoter, has been confirmed in different types of cancers." (PMID 33846573, 2021). "In a comprehensive analysis of three large databases (TCGA, Memorial Sloan Kettering Cancer Cancer (MSKCC) databases, and Geneplus cohort), it was revealed that CCND1 amplifications in patients that receive ICIs is associated with decreased OS in different cancer entities." (PMID 34944992, 2021). "Cyclin D1, a target of miR-503 plays a critical role in various cancers." (PMID 34454450, 2021). "In many cancers, cyclin D1 is one of the downstream components of the PI3K-Akt signalling pathway." (PMID 34087900, 2021). "Moreover, silencing of PDS5B expression promotes cell proliferation via induction of IL-6 secretion and activation of STAT3, and promotion of cyclin D1 expression in human cancer." (PMID 34226509, 2021). "Ubiquitination of CCND1 is achievable in response to IR and, in cancer cells, IR or other DNA-damaging agents may activate selective autophagy." (PMID 34445095, 2021). "In this research, our aim is to find the function of cyclin D1 in transcription in human cancers." (PMID 34335935, 2021). "It is indicated that the effect of SMARCE1 (BAF57) on regulating cyclin D1 splicing may also contribute to cancer progression." (PMID 33670012, 2021). "Together these results define an antagonistic feedback loop and signaling network between TGFβ superfamily members, whereby TGFβ/Smad/cyclin D1 signaling leads to increased cancer stem cell numbers while BMP4 oppose these effects acting as a potent differentiation factor." (PMID 33649296, 2021). "Cyclin D1 stimulates cancer cell growth and affects the anti-cancer effect of adiponectin." (PMID 34485124, 2021). "Assessing the role of each feature of cyclin D1 in cancer progression could aid in the development of therapies that are more precisely targeted and customized." (PMID 34903946, 2021). "There is much less information of PRMT5 and Cyclin E1, which may be due to the higher prevalence of cancers with Cyclin D1 than with Cyclin E1 overexpression." (PMID 34168658, 2021). "Cyclin D1 is frequently overexpressed and/or amplified in many types of cancers, including cSCC." (PMID 33808400, 2021).